SOX10 (SRY-box transcription factor 10)
Diseases named in the same sentence as SOX10 in open-access papers (continued):
Sharing a sentence is not in itself a finding about the gene and the disease.
melanoma (continued). "Another target of PKA could be SOX9 in melanoma cells as it is involved in promoting a cancer stem cell phenotype, contributing to tumour heterogeneity with the crosstalk of SOX10." (PMID 41465475, 2025). "SOX10 is a marker for melanoma plasticity, such as invasive tumor cell behavior." (PMID 41255880, 2025). "SOX10 is a sensitive and relatively specific marker for melanoma nuclei." (PMID 39138753, 2025). "Moreover, in a cohort of melanoma patients, the quartile low-SOX10 group had a significantly higher overall survival than the quartile high-SOX10 group (p = 0.012)." (PMID 40956859, 2025). "In melanocytic lesions, SOX10 is expressed in benign melanocytic nevi, primary cutaneous melanomas, desmoplastic melanomas, both pure and mixed desmoplastic melanomas, and melanoma metastases." (PMID 40507250, 2025). "Notably, PAX3 was significantly upregulated in conjunctival/limbal melanoma tissues compared to healthy counterparts, with expression co-localizing with melanocyte markers (Melan-A, HMB45, SOX10) and the proliferation marker Ki-67 in melanoma cells." (PMID 40216818, 2025). "Other pertinent negative immunostains include hematolymphoid markers (CD45, CD3, CD20, CD79a), myoid markers (smooth muscle actin (SMA), desmin), vascular markers (CD31, CD34), epithelial markers (EMA, keratins), melanoma markers (melanA, SOX10, HMB45, S100), and other markers (ALK, CD30)." (PMID 40563703, 2025). "Next, we investigated whether HK2 contributes to proliferation properties of melanoma cells via the SOX10 UTR." (PMID 40956859, 2025). "In this case, the absence of Hutchinson's sign and negative immunohistochemical staining for melanocytic markers, including Melan-A and SOX-10, helped exclude melanoma as a diagnosis, while the triangular sign and solitary lesions on nails were suggestive of malignancy." (PMID 41589154, 2025). "The oncogenic potential of SOX10 is further demonstrated by its ability to drive the formation of giant congenital naevi and melanoma, while paradoxically, it can also inhibit melanoma cell proliferation through modulation of Notch and WNT/β‐catenin signaling pathways." (PMID 40458894, 2025). "This interaction suggests that preserving wild-type SOX10 function may support the survival and proliferation of melanoma cells." (PMID 41155720, 2025). "SOX10 is a key regulator of melanoma progression and promotes a melanocytic/differentiated state." (PMID 40342816, 2025). "Thus, the PACAP-induced increase in p-SOX9, together with the reduction in SOX10, favours a transcriptional environment that shifts melanoma cells toward a more differentiated and less invasive state." (PMID 41465475, 2025). "The pertinent negative markers include histiocytic markers (CD163, CD14, CD1a, langerin), FDC markers (CD21, CD23, CD35, clusterin, CXCL13), hematolymphoid markers (CD45, CD3, CD20, CD79a), vascular markers (CD31, CD34), melanoma markers (melanA, SOX10, HMB45, S100), and others (ALK, CD30)." (PMID 40563703, 2025). "Melanoma-specific knockout of sox10 reduces tumor burden and induces phenotypic switching." (PMID 40879132, 2025). "The expression of sox10 was also checked in the kita:Ras melanoma biopsies." (PMID 40449994, 2025). "SOX10 is highly sensitive and specific todesmoplastic melanoma." (PMID 40507250, 2025). "Despite these limitations, our approach may be combined with future advancements in scDNA-seq technologies to reduce costs by focusing sequencing efforts on cells of interest only, such as SOX10-positive melanoma cells." (PMID 40004220, 2025). "In this case, the increased level of sox10 transcript was associated with the presence of the zebrafish melanoma mass, which is absent in the wild type (CTL) biopsies." (PMID 40449994, 2025). "SOX10 regulates immune checkpoint protein expression and anti-tumor immunity in melanoma." (PMID 39889187, 2025). "SOX10 deletion sensitizes melanoma to cytokine-induced pyroptosis." (PMID 41235238, 2025).
melanoma (continued). "Furthermore, biomarkers such as TTF-1 and CDX-2 can be used to identify metastatic MCC, whereas LCA, CD99, S100, HMB-45, and SOX-10 can exclude lymphoma, Ewing sarcoma, and malignant melanoma." (PMID 41245381, 2025). "□ Melanoma: Common markers include S-100 protein, SOX-10, Melan A, HMB45, tyrosinase, and MITF." (PMID 40308487, 2025). "Moreover, melanoma tumors are frequently characterized by an inhomogeneous SOX10 expression, as was observed in this study." (PMID 41255880, 2025). "Due to its relationship with aggressiveness in different tumor types, we hypothesized that proteins SOX2, SOX3 and SOX10, in canine melanomas, play a role similar to that observed in human neoplasms." (PMID 41012776, 2025). "Additional ancillary markers such as Melan-A and SOX10 are sensitive for melanocytic differentiation and can help confirm melanocytic lineage; however, they do not distinguish between benign melanocytic proliferations (e.g., nodal nevi) and malignant melanoma." (PMID 40984891, 2025). "This suggests that distinct melanoma cell states are underpinned by SOX10‐mediated network motifs." (PMID 40458894, 2025). "The lesion lacked precursor melanoma and showed a loss of Melan-A expression, with preservation of SOX10 expression." (PMID 40125165, 2025). "Firstly, significant differences in SOX10 expression levels between melanoma and normal skin tissue suggest that SOX10 could act as a marker for differential diagnosis." (PMID 40342816, 2025). "In precursor regions, TRM-like cells could be found in close proximity to MART1+ SOX10+ melanoma cells (inset iii circled regions) and were found infiltrating the tumor bed in VGP areas (insets iv-vi)." (PMID 41279375, 2025). "Among the three validated mRNAs, we were particularly interested in the SOX10 mRNA that encodes the Sex Determining Region Y (SRY)-Box Transcription Factor 10 (SOX10), which has a well-known activity as a transcription factor regulating tumor initiation, maintenance, and progression in melanoma." (PMID 40956859, 2025). "Knockdown of SOX10 inhibits melanoma cell proliferation and suppresses tumor formation in vivo." (PMID 40342816, 2025). "Collectively, these findings underscore how multiple miRNAs, acting individually or synergistically, significantly impact melanoma metastasis and invasion through their ability to modulate SOX10, MITF, and their mutual targets via direct and indirect mechanisms." (PMID 40458894, 2025). "However, HK2 depletion affects melanoma cell migration via other mechanisms, independently of SOX10." (PMID 40956859, 2025). "SOX10 was initially reported as a marker for neurogenic tumors and malignant melanoma." (PMID 40822238, 2025). "At the second time point (t2), we observed a slight increase in the frequency of Sox10+ cells overall, and the appearance of clusters of Sox10+ melanoma cells, which often colocalized with hyperpigmented regions, but could also be amelanotic (site iv)." (PMID 41279375, 2025). "have found that in human patients, virtually all melanomas are SOX10 positive." (PMID 40342816, 2025). "Additionally, we investigated the gene regulatory interactions in melanoma, identifying crucial network motifs that involve SOX10, MITF, and miRNAs." (PMID 40458894, 2025). "Common IHC markers used in melanoma diagnosis include S100, SOX10, Melan-A, and HMB-45." (PMID 40868240, 2025). "However, no comprehensive review has elucidated the interactions between SOX10 and miRNAs in melanoma." (PMID 40458894, 2025). "Pathological analysis showed benign urothelium with intracytoplasmic and subepithelial dark pigments positive for Fontana Masson stain, consistent with melanin, but negative for PASd, iron stain (which cleared with bleach treatment), and melanocytic markers (HMB45, SOX10, S100), ruling out melanoma." (PMID 39906764, 2025).
melanoma (continued). "Studies have shown that SOX10 contributes to melanoma’s adaptive resistance to RAF inhibitors via the ERK1/2/SOX10/FOXD3/ERBB3 signaling pathway.The imperative for developing a prognostic model based on SOX10 is to enhance melanoma patients’ survival rates and refine treatment strategies." (PMID 40342816, 2025). "Besides, while SOX10 knockdown has been shown to promote cell migration, it has also been demonstrated to decrease melanoma cell proliferation and clonogenicity." (PMID 40956859, 2025). "Remarkably, we found that EP300 and SOX10 gene copy numbers are strongly correlated in human melanomas and are reproducibly co-amplified at a high frequency (∼35%–46% of samples) across several melanoma datasets from cBioPortal, including TCGA database." (PMID 38994683, 2024). "Moreover, in melanoma, the phosphorylation of SOX10 by ERK at T240 and T244 residues inhibits SOX10 SUMOylation, dampening its transcriptional activity." (PMID 38331879, 2024). "We conclude that the SOX10/p300 axis is critical to melanoma growth and invasion and that inhibition of p300 KAT activity through A-485 may be a worthwhile therapeutic approach for SOX10-reliant tumors." (PMID 38994683, 2024). "This suggests that SOX10 is a major target of p300 KAT inhibition in human melanoma." (PMID 38994683, 2024). "The examination revealed characteristic cellular features of melanoma, including atypical melanocytes with prominent nucleoli, along with a positive staining pattern for melanoma-specific markers (SOX10, S-100, and HMB45), which definitively confirmed the metastatic origin." (PMID 39553048, 2024). "Given the impact of p300 activity on melanoma growth, direct regulation of MITF transcription by p300, and the concomitant loss of SOX10 and MITF protein expression following p300 inhibition in melanoma cells, we sought to further clarify the connection between SOX10, MITF, and p300." (PMID 38994683, 2024). "This suggests that, as melanomas progress, they may become less dependent on established Sox10 NCC transcriptional networks and survive through alternative transcriptional cell states." (PMID 39092608, 2024). "We therefore suggest that EP300/SOX10 co-amplification in melanoma may serve as a biomarker for tumors which would benefit from therapeutic p300 inhibition." (PMID 38994683, 2024). "SOX10 intra-tumor heterogeneity in melanoma samples was consistent with recent reports." (PMID 38519642, 2024). "Recently, SOX10-positive perivascular cells were taken under consideration in melanoma studies." (PMID 39518110, 2024). "MITFA and SOX10 have previously been identified as specific markers of malignant zebrafish melanomas in the original study, while PAICS and COX6A2 are newly discovered by our study, which actually play important biological roles and molecular functions in tumor development." (PMID 39494219, 2024). "Occasionally, melanoma may lose all of its routine diagnostic markers such as HMB45, MART-1, S100, and SOX-10 indicating dedifferentiation." (PMID 39258061, 2024). "SOX10 also plays a significant role in mediating resistance to BRAF inhibition in melanoma." (PMID 39611156, 2024). "SOX10 was first described in 2008 as a pan-schwannian and melanocytic marker when its expression was reported in all cases of neurofibroma, schwannoma, myoepithelioma of salivary gland, and 97% cases of melanoma." (PMID 38813332, 2024). "Additionally, SOX10 has been shown to play a crucial role in melanoma phenotype switching through repression of a metastatic transcriptional program." (PMID 38994683, 2024). "Besides, the presence of multiple malignant somatic components attributable to melanoma (SOX10+, MART1+, HMB45+, VIM+, S100+/-), leiomyosarcoma (alpha-actin+,desmin+), and PNET (CD99+, αFP+) was documented." (PMID 39605889, 2024). "Additionally, A-485 potently inhibits proliferation of SOX10+ melanoma cells while decreasing invasion in AXLhigh/MITFlow melanoma cells through downregulation of metastasis-related genes." (PMID 38994683, 2024).
melanoma (continued). "The results showed that as the melanoma progressed, the expression of malignant progression marker genes (pmel, mlana, sox10, cdk4, zeb1, and vim) significantly increased, with notable expression differences observed among benign nevi, dysplastic nevi, and invasive melanoma." (PMID 39659584, 2024). "Indeed, our scRNA-seq data identified TIE:EGFP+ macrophage subclusters that express mitfa and/or sox10, providing additional evidence for phagocytosis of melanoma cells." (PMID 38874379, 2024). "Notably, the knockout of SOX10, when simultaneously treating advanced melanoma, can confer resistive mechanisms against chemotherapeutic medications." (PMID 38132479, 2023). "To extend these hypotheses to other melanoma cell lines, we knocked down CDC20 by siRNA and performed quantitative PCR (qPCR) on SOX10 on melanoma cell lines spanning multiple subtypes." (PMID 38030698, 2023). "In addition, Biomarkers such as S100 protein, micropthlamia transcription factor (MITF), tyrosinase and SOX10 are also widely used in the diagnosis of melanoma." (PMID 37427124, 2023). "Furthermore, the knockout or inactivation of the SOX10 gene established its role as a prerequisite for the formation and maintenance of pre-melanoma lesions." (PMID 38132479, 2023). "The MITF and SOX10 genes play roles as master regulators of melanocyte and melanoma development." (PMID 36251678, 2023). "Therefore, SOX10 expression is required for efficient VSVΔ51 infection in melanoma cells, and its expression is downregulated following resistance to MAPK inhibitors." (PMID 38201278, 2023). "Knockdown experiments revealed that suppression of PITX1 resulted in decreased SOX9 expression, whereas overexpression of PITX1 led to activated and increased SOX9 expression, inhibiting the growth and proliferation of melanoma by suppressing SOX10 and SAMMSON." (PMID 37841446, 2023). "However, a study on the reprogramming phase in melanoma suggests MITF/SOX10 and AP1/TEAD as being the master regulators of the proliferative and the invasive transcriptome, respectively." (PMID 36251678, 2023). "However, wild-type VSV infection was similarly reduced in drug-resistant melanoma cells and SOX10 KO cells, analogous to our data with VSVΔ51." (PMID 38201278, 2023). "Therapeutics such as histone deacetylase inhibitors may be used to suppress SOX10 expression, thus leading to the induction of PD-L1 expression on melanoma cells and increased responsiveness to anti-PD-L1 therapies." (PMID 37626741, 2023). "A total of 195 TFs were predicted to be under the regulation of these elements including major, already established transcriptional dependency of melanoma (SOX10 and MITF) or factors like SNAI1 and SNAI2 that drive the transition toward the mesenchymal phenotype." (PMID 37408506, 2023). "Using Vemurafenib to treat advanced melanoma with an observed BRAFV600E mutation, cells acquiring a somatic SOX10 mutation that hinders proper gene product formation allow the tumor to grow unchallenged by therapeutic treatments that would otherwise be effective." (PMID 38132479, 2023). "As S100, WT1, and CD99 may be expressed in both melanomas and various sarcomas, SOX10 was particularly useful in diagnosing this osteoid melanoma." (PMID 37373134, 2023). "Effects of CRISPR/Cas9-mediated SOX10 knockout in MITF-methylated melanoma cells." (PMID 36040798, 2022). "However, when injecting such cells in NSG mice, we observed that the undifferentiated SOX10– melanoma cells developed significantly smaller tumors compared with SOX10+MITF– melanoma cells." (PMID 36040798, 2022). "On the contrary, SOX10 significantly facilitated and maintained melanoma development." (PMID 35611828, 2022). "Finally, we noted the overall similarity in the contour of chromatin accessibility within premalignant melanocytes and melanomas as well as the numerous areas of differential accessibility as, for example, near sox10 and mitfa." (PMID 34791221, 2022).
melanoma (continued). "Reactivation of neural crest genes such as crestin (in zebrafish melanoma) and SOX10 (in zebrafish as well as in human melanoma cell lines) is probably consequent to epigenetic modifications on histones, as shown by some histone markers known as super-enhancers." (PMID 35713744, 2022). "Moreover, expression of NC lineage genes was lost in SOX10– melanoma cells, suggesting that such cells have lost several NC-specific properties." (PMID 36040798, 2022). "Furthermore, qRT-PCR was used to verify the expression of miRNA-222-3p and miRNA-221-3p in melanoma cells and its interaction with SOX10." (PMID 35585935, 2022). "MITF-methylated melanomas have diverse functional phenotypes discriminated by SOX10 expression." (PMID 36040798, 2022). "Specifically, melanoma cells from the different SOX10+ cell lines clustered in small and compact structures maintaining tight cell-to-cell contact, while melanoma cells from the SOX10– cell lines formed considerably larger colonies in which the cells tended to segregate and distribute sparsely." (PMID 36040798, 2022). "We demonstrated reproducible staining with the accurate detection of immune cell markers CD8, CD68, CD16, immune checkpoint PD-L, and melanoma tumour marker SOX10 in a multiplex methodology compared with chromogenic immunohistochemistry and single-plex immunofluorescence staining for all markers." (PMID 35664673, 2022). "Interestingly, when we analyzed the expression of NC-specific genes, we found that SOX10– undifferentiated melanoma cell lines had downregulation of genes expressed in normal melanocytes, with the exception of acquired expression of SOX9." (PMID 36040798, 2022). "Finally, the MITF-negative undifferentiated cells are prone to lose the expression of SOX10, hence acquiring a preneural crest phenotype upregulating SOX9, as demonstrated in MITF-methylated melanoma cells knocked out for SOX10." (PMID 36551603, 2022). "Furthermore, methylation-mediated repression of SOX10 has been reported in a variety of disorders; however, studies addressing the regulation of SOX10 through methylation in melanoma have been limited and contradictory." (PMID 36040798, 2022). "SOX10 expression is used as a marker for melanoma and its role is intriguing." (PMID 35296667, 2022). "In contrast, the SOX10+ MM383 melanoma cell line formed primary tumors in all 10 transplanted mice." (PMID 36040798, 2022). "We then stained a panel of human melanoma samples for YAP localization utilizing SOX10 as a marker for melanoma cells and, in agreement with previous studies, found that multiple melanoma tumors exhibited strong nuclear YAP localization, suggesting Hippo pathway inactivation 31,38." (PMID 35768444, 2022). "Therefore, in this study, melanoma cells were used to investigate the mechanism of curcumin on melanoma in vitro, as well as the role of miR-222-3p and SOX10 in it, aiming to provide new therapeutic options for the clinical treatment of melanoma." (PMID 35585935, 2022). "Furthermore, primary tumors from NSG mice engrafted with SOX10– IGR-39 melanoma cells were significantly smaller compared with primary tumors developed in NSG mice engrafted with SOX10+ MM383 melanoma cell line." (PMID 36040798, 2022). "Genome-wide epigenetic characterization of the 15 melanoma cell lines with MITF promoter hypermethylation using the Illumina EPIC arrays displayed that lack of SOX10 mRNA was associated with hypermethylation of the SOX10 promoter." (PMID 36040798, 2022). "This study unravels a new molecular mechanism of DEPDC1B acting downstream of SOX10 to promote melanoma angiogenesis and metastasis through CDC16 sequestration that stabilizes secreted SCUBE3, which suggests the possibility of targeting SCUBE3 as a therapeutic strategy against metastatic melanoma." (PMID 35088579, 2022). "Depletion of SOX10 in MITF-methylated melanoma cells using CRISPR/Cas9 supported these findings." (PMID 36040798, 2022).